IL6 (interleukin 6)
Diseases named in the same sentence as IL6 in open-access papers (continued):
Sharing a sentence is not in itself a finding about the gene and the disease.
cancer (continued). "Our findings uncover the critical role of MSN in regulating STAT3-mediated cancer stemness via the IL-6/NF-κB signaling axis." (PMID 40696387, 2025). "Another therapeutic function of PCB includes its suppression of cancer through antiproliferative effects on cancer cells and reduction of expression of pro-inflammatory factors like IL-6 and IFN-γ for inflammation reduction." (PMID 40142154, 2025). "This shows that exercise can indeed increase IL-6 levels in cancer patients, but MBI combined with gentle exercise has an even more significant effect in this participant group." (PMID 40281902, 2025). "Preclinical studies across various cancer types have provided substantial evidence supporting the role of IL-6 in promoting cancer progression." (PMID 39858048, 2025). "In conclusion, cembranoids selectively suppress TGF-β-induced IL-6 while preserving canonical Smad signaling, coinciding with reduced cancer cell migration/invasion." (PMID 41373438, 2025). "Thus, our findings suggest that the IL-6–JAK–STAT-signalling-dependent induction of hepatic Pdk3 expression represents a previously unknown pathogenic mechanism underlying metabolic disorder in cancer cachexia." (PMID 40275022, 2025). "Specifically, cytokines like TNF-α, IL-6, IL-18, IL-1β, and INF-γ are implicated in cancer cachexia, promoting elevated energy expenditure, reduced appetite, and skeletal muscle degradation." (PMID 39996717, 2025). "In the realm of cancer cachexia, IL-6 and tumor necrosis factor- α (TNFα) are notable pro-inflammatory cytokines." (PMID 39311910, 2025). "The rationale for the prophylactic use of anti-IL-6 receptor antibodies in combination with ICIs is supported by the favorable safety profile of IL-6 blockade in terms of cancer-related outcomes." (PMID 41019062, 2025). "IL-6 is a proinflammatory cytokine whose excessive signaling is believed to play a key role in cancer progression." (PMID 40317079, 2025). "Concordantly, interleukin‐6 (IL‐6) release effecting bone morphogenic protein (BMP) function leads to loss of protective muscle to nerve signals with denervation and MW in cancer." (PMID 40035088, 2025). "CAF-derived IL-6 contributes to cancer invasion, metastasis, angiogenesis, immune modulation, and drug resistance." (PMID 39780187, 2025). "Specifically murine models in the context of cancer are also in focus of current research for both IL‐6 and GDF‐15." (PMID 41380167, 2025). "Co-culture experiments involving adipocytes and breast cancer cells have revealed heightened expression and secretion of IL-6 by adipocytes, thereby fostering cancer cell invasion and migration." (PMID 41200178, 2025). "Both IL-6 and IL-1b illustrate how the sleep–wake cycle is connected to cytokines that play a role in cancer initiation/progression and how the disruption of the cycle is potentially a risk factor for tumorigenesis." (PMID 40075580, 2025). "IL-6 is a critical yet controversial cytokine within the inflammatory and cancer microenvironments, underscoring the importance of understanding the direction of its secretion for influencing subsequent cytokine secretion or activity of surrounding cells." (PMID 40191548, 2025). "Inflammation has always been an integral part of the HCC disease biology, and the expression of IL-6, IL-8, and IL-1B have all been shown to promote cancer cell stemness by reducing self-renewal pathways." (PMID 41283329, 2025). "These consistent findings across clinical and experimental settings strongly suggest that IL-6 is involved in mediating both therapeutic response and irAEs development in cancer patients." (PMID 40519900, 2025). "It is rich in tumor necrosis factor α (TNF-α), IL-1β, IL-6, and other chemokines and cytokines, which stimulate cancer cell growth, promote the formation of blood vessels, and reshape the extracellular matrix." (PMID 40244135, 2025).
cancer (continued). "Emerging evidence indicates that the NRF2 anti-oxidant pathway mediates resistance to therapy in cancer cells and that IL-6 promotes therapy resistance via NRF2 in SCC." (PMID 40317079, 2025). "Our results revealed the upregulation of IL6 in both the serum and cancer tissues of HCC patients, which was positively correlated with the protein level of MMP9 and linked to a worse prognosis." (PMID 39744421, 2025). "Recent study has identified IL-6 as a predictive factor of poor response to ICIs in large clinical trials of several types of cancer." (PMID 40255422, 2025). "The inflammatory cytokines secreted by leukocytes, such as TNF-α, IL-6, and IL-1β, promote cancer cell proliferation, survival, and resistance to apoptosis." (PMID 39869563, 2025). "IL6 has been shown to be a multifunctional cytokine involved in the regulation of cancer progression and involved in the malignant processes such as EMT, angiogenesis, and treatment resistance." (PMID 39897030, 2025). "A pleiotropic but immunosuppressive function has been observed for IL-6 secretion, from which malignant tumors benefit by enhancing proliferation, survival, invasiveness and metastasis." (PMID 40699630, 2025). "Increased expression of TNF-α and IL-6 can be observed in different animal models of cancer pain, which in turn produce persistent cancer pain and associated inflammation, and inhibition of TNF-α and IL-6 signaling reduced nociception." (PMID 39759851, 2025). "At the same time, interleukin-6 (IL-6) and interleukin-8 (IL-8) create a favorable setting for cancer cells to resist apoptosis – the natural cell death that should occur when something goes wrong." (PMID 40901118, 2025). "Previous research on the correlation between IL-6 and the HPV virus has primarily focused on HPV’s effect on IL-6 secretion from cancer cells." (PMID 39858048, 2025). "We also found upregulation of the IL6/JAK/STAT signaling pathway, which is important in regulating macrophage inflammatory response and implicated in cancer immunity dysfunction." (PMID 41445746, 2025). "Our findings establish CD109 as an essential regulator of IL-6-mediated oncogenic activity promoting cancer cell stemness and antioxidant state in SCC cells, providing mechanistic insights into IL-6-mediated cell survival and resistance to therapy in SCC." (PMID 40317079, 2025). "Interleukin-6 (IL-6) collaborates with TNF-α or acts independently to mediate systemic inflammation in cancer cachexia." (PMID 40519290, 2025). "EGCG exerts anti-cancer activity by targeting multiple cellular processes, such as oxidative stress reduction, and suppression of inflammatory mediators like Interleukin-6 (IL-6) and Tumor Necrosis Factor-α (TNF-α)." (PMID 40918466, 2025). "Cancer-associated adipocytes and fibroblasts secrete paracrine signals such as stromal-derived factor-1 (SDF-1), TGF-β, IL-6, and VEGF." (PMID 40821116, 2025). "In this multicenter, prospective pan-cancer cohort study, serum IL-6 levels were quantified immediately before the first (pre-ICI) and second (post-ICI) cycles of ICI therapy." (PMID 41019062, 2025). "αSMA-positive myCAFs tended to be located near the cancer region, whereas IL-6-positive iCAFs tended to be distant from the cancer region." (PMID 39904796, 2025). "A3A expression has been correlated with IL6 expression in cancer cell lines and primary macrophages." (PMID 40059825, 2025). "Targeted inhibition of IL-6 signaling pathway by monoclonal antibodies or IL-6Rs can produce therapeutic benefits for a variety of malignant tumors." (PMID 40118853, 2025). "IL-6 is one of the most important pro-inflammatory mediators involved in cancer initiation and progression." (PMID 40733274, 2025). "Among the novel biomarkers studied, we found evidence for IL-6 for its potential use in the detection of cardiac dysfunction related to cancer therapy in patients treated with anthracyclines." (PMID 40362309, 2025).
cancer (continued). "For instance, high IL-6 levels in cancer cells allow IL-6 receptor (IL-6R)-targeting aptamers to serve as delivery vehicles for chemotherapeutics." (PMID 40277546, 2025). "P. gingivalis induces the secretion of many cancer-contributing chemokines and cytokines, including Interleukin (IL)-1β, IL-6, IL-8, transforming growth factor (TGF)-β1, epidermal growth factor (EGF), and tumor necrosis factor alpha (TNF-α)." (PMID 41471188, 2025). "The IL-6/JAK/STAT3 pathway is aberrantly hyperactivated in many types of cancers and participates in the activation of CAFs, ultimately leading to poor clinical prognosis." (PMID 40890855, 2025). "For instance, Murray & Wynn (2011) demonstrated that IL-1β and IL-6 are robustly upregulated in classically activated macrophages, driving pro-inflammatory responses in infections and cancer." (PMID 40933659, 2025). "In U2OS and MG-63 OS cells, IL-6 promoted cancer stemness and tumorigenicity by activating the OPN-STAT3 pathway." (PMID 40909292, 2025). "IL-6 facilitates the progression of some types of cancer via the involvement of certain biological mechanisms and cellular processes that involve apoptosis, survival, angiogenesis, invasiveness, metastasis, and metabolism." (PMID 40722593, 2025). "The cytokine IL-6 is secreted by cancer cells undergoing EMT and, in turn, can activate EMT plasticity." (PMID 40059825, 2025). "First, the sample size is relatively small, which is not large enough to fully validate our results and determine clinical applicability of serum IL-6 to diverse cancer patients." (PMID 39781345, 2025). "Previous studies have demonstrated robust cancer-induced systemic changes, characterized by elevated inflammatory mediators such as IL-6, TNF-α, CXCL10, and MMP9." (PMID 41153795, 2025). "Future studies should evaluate the role of IL-6 and CRP in risk stratification for TB associated cancer." (PMID 40475250, 2025). "The interleukin‐6 (IL‐6) family of cytokines has been reported to regulate cachexia in several preclinical cancer models." (PMID 40931444, 2025). "Key cellular contributors include cancer-associated fibroblasts (CAFs), which deposit dense extracellular matrix (ECM) and secrete pro-survival cytokines (e.g., TGF-β, HGF, IL-6), thereby enhancing drug resistance via PI3K/AKT and MAPK pathways." (PMID 40941035, 2025). "Bazedoxifene has been identified as an effective inhibitor of the IL6/GP130/STAT3 pathway, which is implicated in the tumorigenesis and progression of these cancers." (PMID 40201234, 2025). "Various cytokines such as TNF-a, TGF-b, IL-10, IL-1b, and IL-6 are involved in the crosstalk between cancer initiation/progression and sleep–wake cycles." (PMID 40075580, 2025). "Cancer induces systemic inflammation, mainly via IL-6 and TNF-α, which damages endothelial cells and increases the recruitment of inflammatory cells to atherosclerotic plaques." (PMID 39857281, 2025). "A statistically significant difference was noticed between hypoxic and normoxic PANC-1 cells, suggesting that IL-6 expression increased in stress conditions as a resistance mechanism in cancer cells." (PMID 39883638, 2025). "We also found a relationship between EV-TF and IL-6, a marker of systemic inflammation also involved in cancer progression and in VTE, only in patients with C-VTE." (PMID 39858477, 2025). "In the MBI post-intervention studies, most groups showed a mild-to-moderate decrease in IL-6 levels, with only the cancer group showing a moderate increase in IL-6 levels (SMD = 0.24; 95% CI, −0.29 to 0.76)." (PMID 40281902, 2025). "Altogether, our results support a conserved mechanism whereby IL-6–JAK–STAT signalling promotes hepatic PDK3 expression, contributing to mortality linked to cancer." (PMID 40275022, 2025). "STAT3 activation stimulated by IL-6 and various cancers increases the expression of Atrogin-1 and MuRF-1, thereby enhancing the ubiquitin-proteasome system and contributing to muscle degradation." (PMID 40469669, 2025).
cancer (continued). "Immunogenic DCs secrete a set of proinflammatory cytokines (TNF-α, IL-6, 8 and 12), which improve the clinical outcomes in cancer patients." (PMID 40136652, 2025). "Paradoxically, NF-κB also mediates early proinflammatory responses in TAMs via cytokines such as IL-1β and IL-6, which fuel tumorigenesis by promoting cancer cell survival and proliferation." (PMID 40562870, 2025). "In cancer cells, IL6 promotes cell proliferation by both accelerating the cell cycle and preventing apoptosis." (PMID 40427188, 2025). "Selenium inhibits the production of pro-inflammatory cytokines such as interleukin-6 (IL-6) and tumor necrosis factor-alpha (TNF-α), both of which are associated with cancer progression." (PMID 40901095, 2025). "Three cytokines, IL-6, TNF-α, and IL-1β, serve as central mediators of cancer-associated hypercoagulability through distinct but overlapping mechanisms." (PMID 40725619, 2025). "Following L-OHP exposure, IL-6 levels in the co-culture supernatant increased further, reaching 5.2- and 6.8-fold higher than in monocultured cancer cells and fibroblasts, respectively." (PMID 40718440, 2025). "DSPS can promote the proliferation of T lymphocytes in cancer patients by regulating the expression of cytokines (such as IL-2, IL-4, IL-6, IFN-γ)." (PMID 40867887, 2025). "Cancer serum was incubated with control IgG or neutralizing antibodies targeting IL-6, G-CSF, TNFα, and IFNγ before injection into MDX mice." (PMID 41322654, 2025). "IL‐6, a pleiotropic cytokine, plays a crucial role in the initiation and progression of various types of cancers." (PMID 40620232, 2025). "Persistent IL-6 activity can promote immune-suppressive signals and hinder the establishment of an effective immune response against cancer cells." (PMID 41162970, 2025). "Altogether, our data demonstrate that housing temperature impacts metabolic and molecular responses to cancer, including alterations in glucose metabolism, and IL‐6‐driven inflammatory responses." (PMID 40237521, 2025). "During chronic inflammation induced by cancer, tissues responding to IL-6 gradually become resistant, correlating with elevated IL-6 levels." (PMID 40558287, 2025). "Here, live PANC-1, SW620, and MCF7 cancer cells were added to TGFβ-1 (4.0 × 10−3 μg/mL), IL-6 (4.1 × 10−5 μg/mL), HGF (5.97 × 10−4 μg/mL), or untreated together with sialidase substrate 4-MUNANA (emission 450 nm, excitation 365 nm) for 1 min." (PMID 40227834, 2025). "For example, IL-6 secreted by adipocytes has been shown to be crucial in increasing cancer aggressiveness." (PMID 41271789, 2025). "This pattern is consistent with another meta-regression examining the effects of exercise on circulating IL-6 concentrations in cancer patients." (PMID 41583457, 2025). "CD10+GPR77+ CAFs supply the TME with IL-8 and IL-6, which through the activation of NF-κB signaling via p65 phosphorylation and acetylation, protect cancer stem cells from chemotherapy-induced cell death." (PMID 40940764, 2025). "IL-6 can activate the STAT3 pathway in cancer cells, upregulating anti-apoptotic and drug-efflux proteins, contributing to chemotherapy resistance." (PMID 40404908, 2025). "For example, HY-PDT increases pro-inflammatory cytokines like IL-8 and IL-6 in cancer cells, while reducing immunosuppressive factors such as PTX3." (PMID 39857765, 2025). "The miR-146b-5p/IRAK (Interleukin-1 receptor-associated kinase 1) interaction also suppresses NF-κB, inhibiting the production of IL-6 (interleukin-6) and IL-8 (interleukin-8), which contribute to osimertinib resistance in this type of cancer." (PMID 40283927, 2025). "In the subgroup analysis of CNS, qigong and yoga increased the levels of BDNF but decreased IL-6; however, in the subgroup analysis of cancer, the levels of IL-6 were increased." (PMID 40281902, 2025). "This indicates that housing temperature differentially influences the IL‐6 response to cancer from thermogenic tissues, especially in BAT." (PMID 40237521, 2025).
cancer (continued). "In OC, IL6 via STAT3 promotes the expression of CD44, a transmembrane glycoprotein associated with cancer cell stemness." (PMID 40427188, 2025). "This suggests that the upregulation of COL11A1 and the downregulation of CAV1, CXCL12, and SPTBN1 in the cancer microenvironment led to the downregulation of IL-6 and IL-33." (PMID 40898538, 2025). "Gene expression analysis revealed significant modulation of key genes involved in cancer progression, including upregulation of IL-6, and downregulation of anti-apoptotic genes such as BCL2, HIF, and Survivin." (PMID 41310357, 2025). "Consistent with this phenotype, PT-associated macrophages expressed inflammatory cytokines (TNF, IL6) and pro-tumorigenic factors (CCL2, CCL3, CCL4, CXCL16) linked to cancer progression and invasiveness." (PMID 41346635, 2025). "Neutrophils also contribute to cancer progression by releasing cytokines and growth factors, such as IL-6, TNF, epidermal growth factor, hepatocyte growth factor (HGF), and platelet-derived growth factor." (PMID 40027124, 2025). "Our studies also showed overexpression of IL‐6 gene in untreated cancer cells and CT efficiently reduced its expression indicating its beneficial effects in the treatment of GBM." (PMID 39803280, 2025). "Our findings demonstrate that QFG ameliorates cancer cachexia through microbiota modulation and IL-6/NF-κB inhibition, providing a novel multi-targeted approach for cachexia treatment." (PMID 40883855, 2025). "In adult cancers, acquired oncogenic alterations and age-related immune decline contribute to altered expression of NF-κB, IL-6 (a downstream target of NF-κB), and STAT3 signaling, altering immune recognition and cellular senescence." (PMID 39796780, 2025). "Studies have demonstrated that IL-6 and signal transducer and activator of transcription (STAT) are linked to the growth and progression of various cancers, particularly those of the lungs, prostate, kidneys, and breasts." (PMID 41179937, 2025). "Previous studies showed that aberrantly elevated expression of GCS in turn promotes the overexpression of ABCB1, FGF2, and IL6 in cancer cells." (PMID 40507922, 2025). "As mentioned in the previous section, IL-6 impacts cancer progression via key signaling cascades, notably the IL-6/JAK/STAT3 pathway, which plays a critical role in malignant tumor development, as well as invasion and metastasis." (PMID 40868199, 2025). "In the TME,cytokines such as TGFβ and IL-6 have been shown to modulate ANGPTL4 expression in cancer cells." (PMID 40616161, 2025). "Among the biomarkers studied, we found evidence only for IL-6 for its potential use in the detection of cardiac dysfunction related to cancer therapy in patients treated with anthracyclines." (PMID 40362309, 2025). "CYP4F2-mediated 20-HETE production also triggered the production of interleukin-6 (IL-6) and TGF-β in cancer-associated fibroblasts (CAF) leading to immune evasion through the GPR75-STAT3-c-Jun axis." (PMID 40858268, 2025). "Although IL-6 therapies have been successful in the treatment of inflammatory conditions, there has been little experience in patients with cancer." (PMID 40255422, 2025). "Since IL-6 plays a critical role in initiating and maintaining inflammation that promotes cancer progression, this cytokine is suggested to be a cancer biomarker." (PMID 41305639, 2025). "The inhibition of IL-6 can affect cancer cell proliferation and metastasis by influencing cancer cells directly or via TME." (PMID 38715108, 2024). "Therapy with GLP-1 RA reduced ferroptosis and systemic/myocardial levels of NLRP-3, MyD88, IL-1, IL-6 and IL-18, supporting their use in cancer patients treated with anthracyclines and ICIs." (PMID 39457081, 2024). "The TME inflammatory cells and cancer cells are known to secrete several cytokines, such as IL-6, IL-10, IL-13, VEGF, and TGF-β." (PMID 38384463, 2024).